VDR (vitamin D receptor)
Diseases named in the same sentence as VDR in open-access papers (continued):
Sharing a sentence is not in itself a finding about the gene and the disease.
pancreatic cancer (continued). "Combined with our clinical data, we postulate that changes in VDR expression and function in the tumor stroma determined by rs2853564 might affect the clinical course of pancreatic cancer." (PMID 30107003, 2018). "Third, VDR was recently identified as a gemcitabine sensitizer in pancreatic cancer cells in an in vitro screen, and in a study of transplanted murine tumor cells into immuno-competent mice the vitamin D analog calcipotriol enhanced the antitumor effect of gemcitabine." (PMID 28702373, 2017). "Whether up-regulation of the VDR in pancreatic cancer can be seen as a defense mechanism to make use of the locally available 1,25(OH)2D3 more efficiently remains to be investigated." (PMID 25090635, 2014). "However, the future prospective examination of VDR levels in patients with pancreatic cancer is definitely warranted." (PMID 24011168, 2013). "Besides, VDR is abundantly expressed in cancer tissues with high levels of differentiation but has low or undetectable levels of expression in cancer tissues with moderate or low levels of differentiation in pancreatic carcinoma." (PMID 38639057, 2024). "Thus, expression of VDR in cancer cell and stroma cell may be a therapeutic target for pancreatic cancer." (PMID 28969079, 2017). "Although in vitro studies have identified vitamin D and its receptor as potential targets for inhibiting pancreatic cancer development or progression, genetic studies to date have not identified an association between the 25(OH)D, the VDR, and pancreatic cancer." (PMID 26867933, 2016). "Collectively, these findings show calcitriol as the dominant inducer of VDR, and hyperthermia as the primary activator of HSP70 in pancreatic tumor cells." (PMID 41282147, 2025). "For the first time, we demonstrated that, due to the induction of VDR, vitamin D was able to oppose the EMT induced by TGFβ in a pancreatic cancer model." (PMID 34208208, 2021). "A study also indicated that low level of vitamin D receptor (VDR) was correlated with poor prognosis and survival rate in pancreatic cancer patients." (PMID 33730072, 2021). "Beyond the mechanisms described, the molecular basis of FoxM1 dysregulation has been also related to the capability of vitamin D receptor (VDR)/FoxM1 axis to affect cell stemness and to induce an invasive and metastatic phenotypes in pancreatic cancer." (PMID 28770020, 2017). "Activation of VDR by vitamin D or a vitamin D analogue interferes with TGF-β signaling and renders CAFs less active, and VDR-mediated manipulation of the tumor stroma has shown promise in enhancing the efficacy of pancreatic cancer therapy." (PMID 32434573, 2020). "SNPs near the VDR (rs2239186), LRP2 (rs4668123), CYP24A1 (rs2762932), GC (rs2282679), and CUBN (rs1810205) genes were the top SNPs associated with pancreatic cancer (p-values 0.008–0.037), but none were statistically significant after adjusting for multiple comparisons." (PMID 25799011, 2015).
secondary hyperparathyroidism (48 papers, 2012 to 2025). Overproduction of parathyroid hormone in response to influence external to the parathyroid glands. "Nutritional vitamin D reliably corrects deficiency and improves laboratory profiles; VDR activators (VDRAs) suppress secondary hyperparathyroidism (SHPT)." (PMID 41164167, 2025). "Deficiency of vitamin D or defective activation of VDR by its ligand, 1,25-dihydroxy vitamin D results in secondary hyperparathyroidism, angiotensin II-mediated renal damage and renal disease pathogenesis." (PMID 31822280, 2019). "Employing this genetic loss-of-function model, we found that 5/6-Nx induced secondary hyperparathyroidism and bone loss in Fgf23/VDR mice, similar to WT mice." (PMID 29942284, 2018). "Also, miR-27b inhibits the expression of the VDR gene encoding the nuclear vitamin D receptor, thereby reducing cell responsiveness to vitamin D, contributing to the development of secondary hyperparathyroidism." (PMID 40217882, 2025). "Therefore, the aim of this study was to examine the influence of vitamin D receptor (VDR) polymorphisms on secondary hyperparathyroidism and its association with vitamin D levels in black and white South African study participants." (PMID 29415666, 2018). "VDR polymorphisms are associated with adverse outcomes of transplantation such as the increased risk of graft rejection and viral infections, the severity of secondary hyperparathyroidism, bone density of kidney recipients, and an increased risk for bone diseases after transplantation." (PMID 33801744, 2021). "Therefore, the detrimental effects of global VDR deficiency in MI mice may be attributed to hypocalcemia and secondary hyperparathyroidism." (PMID 32899880, 2020). "Indeed, most studies have been aimed at determining whether VDR polymorphisms could be involved in the development of secondary hyperparathyroidism (sHPT), one of the main complications in patients with CKD." (PMID 24618509, 2014). "Dr. Slatopolsky illustrated the role of vitamin D in calcium and bone metabolism and the malfunction of the vitamin D receptor in secondary hyperparathyroidism." (PMID 39364464, 2024). "Secondary hyperparathyroidism among donors is potentially treatable by therapy with vitamin D3 or activated vitamin D receptor agonists, such as calcitriol or paricalcitol." (PMID 38265798, 2024). "The search strategy utilized a combination of Medical Subject Headings (MeSH) terms and keywords, such as VDR gene polymorphisms, HTRO, secondary hyperparathyroidism, ESRD, and hemodialysis." (PMID 39156357, 2024). "Vitamin D receptor activators (VDRAs) have long been the mainstay of treatment for secondary hyperparathyroidism in patients undergoing hemodialysis." (PMID 36104443, 2022). "The VDR Bb genotype is an independent predictor of developing secondary hyperparathyroidism in patients with end stage kidney disease." (PMID 29415666, 2018). "In order to prevent secondary hyperparathyroidism in vitamin D receptor mutant mice, all mice were maintained on a rescue diet enriched with calcium, phosphorus, and lactose." (PMID 30273386, 2018). "Paricalcitol is a selective vitamin D analog, a VDR activator used mostly in the treatment of secondary hyperparathyroidism." (PMID 30011902, 2018). "Paricalcitol, a third generation analogue of vitamin D2, is an activator of VDR and is used for secondary hyperparathyroidism." (PMID 29257109, 2017). "Paricalcitol (a well-known vitamin D analog) is a selective VDR activator which is registered and used in secondary hyperparathyroidism." (PMID 29194370, 2017). "We used data from a prospective cohort of Japanese hemodialysis patients with secondary hyperparathyroidism; the criteria were: intact parathyroid hormone concentrations ≥ 180 pg/mL or use of an intravenous or oral vitamin D receptor activator." (PMID 27764168, 2016). "Activators of vitamin D receptor (VDR) are used to treat secondary hyperparathyroidism in PD patients." (PMID 26556413, 2014).
secondary hyperparathyroidism (continued). "Vitamin D receptor activators are used routinely for the treatment of secondary hyperparathyroidism." (PMID 24678415, 2014). "Severe uremia is complicated by secondary hyperparathyroidism with hyperplasia of the parathyroid glands and is characterized by low parathyroid gene expression of CaR and VDR." (PMID 23094155, 2012). "Paricalcitol is a vitamin D receptor activator used to treat secondary hyperparathyroidism." (PMID 38700923, 2024). "VDR-null mice on a normal diet develop severe secondary hyperparathyroidism." (PMID 32899880, 2020). "In Fgf23/VDR compound mice lacking Fgf23, 5/6-Nx induced secondary hyperparathyroidism and bone loss." (PMID 29942284, 2018). "In a second study, we aimed to study whether RD with additional 1 and 2% calcium (in total 3 and 4% of the diet) is able to prevent secondary hyperparathyroidism in the VDR KO mice." (PMID 28443031, 2017). "However, VDR KO mice are hypocalcaemic and characterized by a secondary hyperparathyroidism and a rickets phenotype." (PMID 28443031, 2017). "Vitamin D Receptor (VDR) Knockout (KO) mice that suffer from a secondary hyperparathyroidism show a series of metabolic disturbances, making it impossible to distinguish between causal effects of VDR and secondary effects caused by pathological PTH concentrations." (PMID 28443031, 2017). "Development of secondary hyperparathyroidism could be due to early disturbances on the local calcium sensing receptor, early decline in parathyroid klotho and possibly lower expression of the vitamin D receptor." (PMID 26566277, 2015). "Therefore, the increased renin mRNA expression found in VDR-null mice fed the normal diet and the subsequent cardiovascular changes in these animals may be due to secondary hyperparathyroidism." (PMID 32899880, 2020). "Targeted therapeutics, such as phosphate binders and vitamin D receptor agonists, can aid in treating CKD-induced secondary hyperparathyroidism by reducing serum phosphate levels and increasing osteopontin levels, which regulate bone remodeling." (PMID 39195755, 2024). "Reduced activation of the vitamin D receptor in CKD, leading to increased expression of PTH and growth of the parathyroid glands, plays a critical role in the pathogenesis of secondary hyperparathyroidism." (PMID 24511210, 2014). "Secondary hyperparathyroidism (s-HPT) in uremia is characterized by decreased expression in the parathyroids of calcium sensing (CaR) and vitamin D receptors (VDR)." (PMID 23094155, 2012). "The J-DAVID was a 48-month, open-label, randomized controlled trial comparing oral alfacalcidol with no vitamin D receptor activators use in terms of cardiovascular events among 976 hemodialysis patients without secondary hyperparathyroidism." (PMID 36104443, 2022). "Thus, we cannot help wondering should we still use repeated non-selective VDR activator in poorly controlled secondary hyperparathyroidism." (PMID 26058796, 2015). "Paricalcitol (19-nor-1,25-hydroxi-vitamin D2), a selective, new generation vitamin D receptor activator, has been proven to be beneficial in the control of secondary hyperparathyroidism both in hemodialysis and predialysis patients with less calcemic and phosphatemic effects." (PMID 24511210, 2014). "In the last decade, one of the most relevant therapeutic innovations in the field of CKD has been the introduction of paricalcitol (19-nor-1,25-dihydroxyvitamin D2), a selective activator of the vitamin D receptor for the prevention and treatment of secondary hyperparathyroidism." (PMID 24511210, 2014). "Here, we aimed to explore further the secondary hyperparathyroidism independent role of vitamin D signalling in the pathophysiology of myocardial infarction by inducing experimental myocardial infarction in 3-month-old, male, wild-type mice and in mice lacking a functioning vitamin D receptor." (PMID 30273386, 2018).
secondary hyperparathyroidism (continued). "It should, however, be emphasized that experimental secondary hyperparathyroidism does not fully resemble the advanced hyperparathyroidism with clonal transformation which is seen in humans, and it can therefore not be ruled out that CaR or VDR promoter methylation might exist in the human setting." (PMID 23094155, 2012).
type 1 diabetes (44 papers, 2009 to 2025). "The abundant presence of pathogenic bacteria found in the patient is based on her genetic condition of type 1 diabetes and the presence of pathogenetic variants of VDR." (PMID 39451399, 2024). "Genetic studies have focused on VDR, which harbors many polymorphisms, but yielded divergent results about its predisposing influence on the development of type 1 diabetes." (PMID 37170809, 2023). "starts from the assumption that variants of the VDR were associated with type 1 diabetes and thyroidal autoimmunity and goes on to analyze the VDR polymorphisms in Addison’s disease." (PMID 36313775, 2022). "A study from Japan showed a significantly high association between VDR gene BsmI polymorphism allele B and the acute-onset type 1 diabetes." (PMID 30845908, 2019). "In another study, researchers found that Staphylococcus aureus is associated with the vitamin D receptor (VDR) polymorphisms in patients with type 1 diabetes." (PMID 30863376, 2019). "On the other hand, the vitamin D receptor (VDR) is present in the human retina, and polymorphisms of VDR gene are related to retinopathy in patients with type 1 diabetes." (PMID 24251044, 2013). "Study on VDR polymorphism for the whole gene indicated susceptibility for type 1 diabetes." (PMID 26576069, 2015). "The vitamin D receptor (VDR) gene regulates insulin secretion from the pancreas and acts as a mediator of the immune response through vitamin D. Polymorphism in VDR causes alterations in the functioning of vitamin D, leading to type 1 diabetes (T1D) predisposition." (PMID 29333433, 2017). "Hence, there may exist a gender-dependent effect, which has been also suggested to the relationship between VDR gene polymorphism and development of diabetes type I." (PMID 25059118, 2014). "The connections between serum 25(OH)D concentration and SNPs in the VDR (rs4516035) and GC (rs12512631) genes were more pronounced in mothers whose children developed type 1 diabetes." (PMID 38613027, 2024). "“cystic fibrosis,” “vitiligo,” “type 1 diabetes,” “vitamin D receptor,” “betamethasone,” and “anti-inflammatory drugs” first appeared in the outermost layer." (PMID 35601441, 2022). "Certain VDR genes were further investigated for 1692 children from DAISY cohort, and an association with type 1 diabetes progression and polymorphism of genes was concluded; however, large cohort studies are required to replicate such data." (PMID 26576069, 2015). "A link between type 1 diabetes and VDR in the β-cells of the endocrine islets has been suggested previously." (PMID 25090635, 2014). "Most genetic studies of vitamin D and type 1 diabetes have focused on the vitamin D receptor (VDR)." (PMID 32764491, 2020). "Moreover, vitamin D receptor (VDR) polymorphisms have been investigated in type 1 diabetes, and some studies have reported that individual VDR polymorphisms seem not to be associated with type 1 diabetes risk." (PMID 40302967, 2024). "Since the VDR is known to regulate the expression of at least 500 genes, some of these genes may influence the development of the immune system and therefore early programming of type 1 diabetes." (PMID 28976992, 2017). "Vitamin D regulates several immune genes as identified through genome wide studies by VDR chromatin immunoprecipitation followed by mass DNA sequencing (CHIP-seq) where VDR binding to autoimmune susceptibility loci was identified amongst them type 1 diabetes sites." (PMID 28425954, 2017). "It is important with regards to therapeutic application of ex vivo-expanded autologous Treg to investigate whether triggering the VDR pathway also increases Tregs in T cells from patients with type 1 diabetes, similar to what we had shown in human CD3+ T cells from control subjects." (PMID 25279717, 2014). "Taken together, these observations led to the conclusion that in vitro, VDR agonists can promote expansion of CD4+CD25highCD127low Tregs in control subjects and patients with type 1 diabetes." (PMID 25279717, 2014).
type 1 diabetes (continued). "Thus, the stronger association between SNPs and serum 25OHD concentration in mothers of type 1 diabetic patients that was seen in the present study may not associate directly with type 1 diabetes, but may be a marker of a difference in vitamin D metabolism and /or in the function of the VDR." (PMID 28976992, 2017).
alopecia (43 papers, 2007 to 2026). Hair loss usually from the scalp. "While VDR polymorphisms have been identified in patients with alopecia, their functional implications for hair growth and treatment outcomes remain poorly understood, making it challenging to predict individual responses to vitamin D‐based therapies." (PMID 41473843, 2026). "Personalized approaches integrating VDR polymorphism profiling with biomarker‐guided treatment selection enable more effective, individualized therapies for alopecia based on comprehensive understanding of VDR's roles in hair follicle homeostasis." (PMID 41473843, 2026). "It is noted that compounds that promote Shh, Wnt, and Bmp signaling pathways have the potential to become therapeutic agents for alopecia and skin-related disorders derived from VDR deficiency." (PMID 39796272, 2025). "VDR is necessary to maintain hair follicle homeostasis, and its deficiency leads to alopecia, as has been shown in mouse and rat models." (PMID 39063155, 2024). "Dysfunction of the VDR has also been linked to alopecia, as hair loss is a prominent feature in vitamin D-dependent rickets type 2A and mice lacking VDR." (PMID 37673445, 2023). "The child we are reporting has total alopecia which supports the possibility of VDR mutation in the DNA-binding domain with severe hormone resistance." (PMID 34508408, 2021). "Alopecia occurs in approximately two-thirds of cases, consequent to a loss of vitamin D receptor activity within keratinocytes." (PMID 33004071, 2020). "The Vitamin D receptor (VDR) plays a key role in hair growth, and human VDR mutations can lead to alopecia." (PMID 31309000, 2019). "We report a case of HVDRR with heterozygous mutation in the VDR gene, neonatal alopecia, and a severe clinical phenotype diagnosed at the age of 30 months who showed unsatisfactory response to traditional therapy." (PMID 30555810, 2018). "Functional analyses of several LBD mutants associated with alopecia show an inability of the VDR to interact with the RXR, but the mechanism by which LBD mutants cause alopecia is not well understood." (PMID 28698609, 2017). "Hereditary 1,25-dihydroxyvitamin D-resistant rickets (HVDRR) is a rare disorder, caused by bialellic mutations of the vitamin D receptor (VDR) gene, sometimes associated with alopecia." (PMID 28698609, 2017). "Herein, we identified a novel missense mutation located on the LBD of the VDR in a patient with severe HVDRR with alopecia." (PMID 28698609, 2017). "Though there is genotype-phenotype variability, the severity of alopecia and hormone resistance seems mostly to depend on the different types of VDR mutation in these patients." (PMID 27796266, 2017). "Mice and human patients with impaired vitamin D receptor (VDR) signaling have normal developmental hair growth but display aberrant post-morphogenic hair cycle progression associated with alopecia." (PMID 27898044, 2016). "Mutations in the DNA binding domain (DBD) of the VDR gene interfere with VDR–DNA interactions and result in the loss of VDR function, and these are usually associated with alopecia." (PMID 28377956, 2015). "Nonsense mutations, missense mutations in the VDR DNA binding domain, and mutations affecting the VDR-RXR dimerization cause alopecia, while mutations affecting the ligand-mediated transactivation and co-activator recruitment do not affect hair growth." (PMID 26422470, 2015). "It has recently been reported that the mechanism by which VDR loss leads to postnatal alopecia is via progressive stem cell depletion." (PMID 18213391, 2008). "Hence, we explored the possibility of using gene- and genome-editing therapies for treating alopecia caused by VDR deficiency." (PMID 37898650, 2023). "We identified a novel missense mutation of the VDR gene that causes HVDRR with alopecia." (PMID 28698609, 2017). "In conclusion, we identified a novel missense mutation of VDR causing HVDRR with alopecia." (PMID 28698609, 2017).